IL6 (interleukin 6)
Diseases named in the same sentence as IL6 in open-access papers (continued):
Sharing a sentence is not in itself a finding about the gene and the disease.
mantle cell lymphoma (13 papers, 2016 to 2025). Mantle cell lymphoma is a rare form of malignant non-Hodgkin lymphoma affecting B lymphocytes in the lymph nodes in a region called the ``mantle zone''. "In the case of mantle cell lymphoma (MCL), the association between TG2 and IL6 activates autophagy, promoting MCL cell survival." (PMID 40227235, 2025). "In a previous study, a positive regulatory loop was found among TGM2 (TG2)-NF-ĸB/NF-κB signaling, IL-6, and autophagy in cancer, as exemplified by mantle cell lymphoma as the model system in that study." (PMID 39654623, 2024). "For instance, β-catenin can inhibit the nuclear transcription of NF-κB and can, therefore, suppress the production of cytokines, such as IL-6, IL-18, and IL-1β, in mantle cell lymphoma (MCL)." (PMID 37189739, 2023). "Other studies have also proved that high level of IL-6 is implemented as a potential negative biomarker for the growth of hematologic malignancies like Hodgkin’s lymphoma (HL), extranodal natural killer T cell lymphoma (ENKTL) and mantle cell lymphoma (MCL)." (PMID 36104733, 2022).
muscular dystrophy (13 papers, 2014 to 2025). Muscular dystrophy (MD) refers to a group of more than 30 genetic diseases characterized by progressive weakness and degeneration of the skeletal muscles that control movement. "For example, in alive mdx mice, a reduction in IL-6 was associated with attenuated muscular dystrophy, whereas overexpression of IL-6 led to more severe symptoms." (PMID 40211386, 2025). "Membrane fragility caused by muscular dystrophy leads to intracellular Ca2+ imbalance, which in turn leads to mitochondrial dysfunction and interleukin-6 (IL-6)-mediated ROS release." (PMID 35372342, 2022). "Nevertheless, this compensatory mechanism is impinged by factors that are associated with the pathogenesis of muscular dystrophy, such as IL-6." (PMID 28845212, 2017). "In contrast, persistent inflammatory conditions, including muscular dystrophy, are associated with long-lasting elevated systemic IL6 levels." (PMID 26137572, 2015). "In this study, we provide evidence that interleukin-6 (IL-6) is causally linked to the pathogenesis of muscular dystrophy." (PMID 26251044, 2015). "Chronic increases in the levels of the inflammatory cytokine interleukin-6 (IL-6) in serum and skeletal muscle are thought to contribute to the progression of muscular dystrophy." (PMID 29078808, 2017). "In contrast, increased circulating levels of IL-6 perturb the redox signaling cascade, even prior to the necrotic stage, leading to severe features and progressive nature of muscular dystrophy." (PMID 28845212, 2017). "The major findings of this study indicate that inhibition of Il6 activity is a possible therapeutic strategy to counteract necrosis and the consequences of chronic inflammation in muscular dystrophy." (PMID 26137572, 2015). "Despite a focus on its pro-inflammatory nature, IL-6 was shown to promote wound healing in response to chemically-induced burns and suppress inflammation in murine models of alveolar endotoxemia and muscular dystrophy." (PMID 24736635, 2014). "Increased levels of IL-6 induced, in mdx/IL6 mice, the severe features and progressive nature of human DMD, in a stage normally spared by the absence of dystrophin, suggesting that IL-6 is causally linked to the pathogenesis of muscular dystrophy." (PMID 26251044, 2015). "Thus, in the context of muscular dystrophy, increased circulating levels of IL-6 might synergize with other factors, creating an hostile microenvironment and exacerbating the dystrophic phenotype." (PMID 26251044, 2015). "This indicates that muscular dystrophy does not further increase the effects of IL-6 on growth defect." (PMID 26251044, 2015).
papillary thyroid carcinoma (13 papers, 2016 to 2026). "For instance, while research has shown that interleukin-6 can induce dedifferentiation in papillary thyroid carcinoma, other studies have found that interleukin-6 expression levels decrease in specific anaplastic thyroid cancer cell lines." (PMID 40072746, 2025). "Punicalagin (PUN), an active component from pomegranate, induced the senescence of human papillary thyroid carcinoma cells by increasing the expression of p21, interleukin-6 (IL-6), and IL-1β via nuclear factor NF-κB." (PMID 36834846, 2023). "We also investigated the IL-6 protein immune-histochemical expression in a retrospective study of 114 patients with papillary thyroid carcinoma and 39 patients with follicular thyroid carcinoma." (PMID 34284788, 2021). "In this study, we estimated serum concentrations of leptin, adiponectin, chemerin, interleukin-6 (IL-6), and vitamin D in patients with papillary thyroid cancer (PTC)." (PMID 30627158, 2018). "This study sought to reveal the significance of IL-6 in papillary thyroid carcinoma by determining its circulating levels, tumoral protein, and mRNA expressions." (PMID 27034885, 2016). "Thus, the goal of this study was to examine the role of IL-6 in benign and papillary thyroid cancer patients and correlate the results with clinicopathological parameters and disease outcome of PTC patients." (PMID 27034885, 2016). "This regulates the interleukin 6 (IL‐6)/Janus kinase (JAK2)/STAT3 signaling pathway, inhibiting glycolysis and tumor growth in papillary thyroid carcinoma (PTC) cells." (PMID 39802639, 2025). "One study has demonstrated that interleukin-6 activates the MAPK and JAK pathways in papillary thyroid cancer cells, leading to their dedifferentiation." (PMID 40072746, 2025). "However, in papillary thyroid cancer, FTO acts as a tumor suppressor to inhibit APOE expression and hinder glycolysis via the IL-6/JAK2/STAT3 signaling pathway." (PMID 41184232, 2025).
pericardial effusion (13 papers, 2012 to 2025). Fluid collection within the pericardial sac, usually due to inflammation. "Elevated VEGF and IL-6 may be associated with the cause of pleural and pericardial effusions in idiopathic RS3PE syndrome." (PMID 27439425, 2016). "Elevated vascular endothelial growth factor and interleukin-6 may be associated with the cause of pleural and pericardial effusions in idiopathic remitting seronegative symmetrical synovitis with pitting edema syndrome." (PMID 27439425, 2016). "Remarkably, the patient’s pericardial effusion was completely resolved and IL-6 levels were significantly reduced (172.4 → 31.5 pg/mL) following this combined therapy." (PMID 40677713, 2025). "Additional analysis revealed a correlation between pericardial effusion and IL-6 levels (p = 0.27), D-dimer (p < 0.001), and PCT (p = 0.049)." (PMID 38138278, 2023). "The patients with pericardial effusions presented with elevated levels of IL-6 (168.52 vs. 67.53 ng/mL), D-dimer (2925.13 vs. 1207.69 ngFEU/mL), and PCT (11.58 vs. 5.54 ng/mL) compared to those without pericardial effusions, respectively." (PMID 38138278, 2023). "In contrast, a systematic analysis of pericardial interleukin-6, interleukin-8, and interferon-γ investigated 101 patients with pericardial effusion." (PMID 22577248, 2012). "Correlations among antibody levels, hsCRP, IL-6, and pericardial effusions." (PMID 35389890, 2022). "Furthermore, vascular endothelial growth factor and interleukin-6 decreased when the pleural and pericardial effusions disappeared." (PMID 27439425, 2016). "Chronic immune activation and a persistent inflammatory state, with increased blood levels of the inflammatory cytokines–TNFα, IL-6, and CRP, associated with a direct cardiac involvement may induce pericardial effusions, with a lower occurrence among patients under antiretroviral therapy." (PMID 36013560, 2022). "Furthermore, pericardial effusion most primarily caused by cancer invasion and immune reaction to chemotherapy, and therefore contains leukocytes and inflammatory cytokines, such as TGF-β, IL-1, and IL-6, directly affecting the electric activity of atrial myocardium and facilitating onset of AF." (PMID 37519821, 2023). "After steroid therapy, levels of serum IL-6 and VEGF decreased when pleural and pericardial effusions disappeared." (PMID 27439425, 2016). "In our patient, serum IL-6 and VEGF were also markedly elevated when pleural and pericardial effusions were increased." (PMID 27439425, 2016). "We observed significantly elevated serum levels of IL-6 in the children with small pericardial effusions compared to those without, 191 ± 53 ng/L vs. 88 ± 27 ng/L, p = 0.041." (PMID 38138278, 2023).
POEMS syndrome (13 papers, 2012 to 2025). POEMS syndrome is a paraneoplastic syndrome characterized by polyradiculoneuropathy (P), organomegaly (O), endocrinopathy (E), clonal plasma cell disorder (M), and skin changes (S). "The pathogenesis mechanism of POEMS syndrome remains unclarified, but it may be linked to cytokine imbalances, including transforming growth factor β1 (TGFβ1), interleukin-6 (IL-6), and serum vascular endothelial growth factor (VEGF)." (PMID 40589976, 2025). "In the meantime, our results establish that IL-6 is a clinically important biomarker among patients with POEMS syndrome." (PMID 40646134, 2025). "We have demonstrated the clinical import of baseline IL-6 levels among patients with POEMS syndrome." (PMID 40646134, 2025). "In contrast to MCD, where interleukin-6 (IL-6) is the primary cytokine, POEMS syndrome's cytokine increase is predominantly VEGF, making it an important target for therapeutic approaches." (PMID 39398672, 2024). "Multiple proinflammatory cytokines such as interleukin-1, TNF-α, and IL-6 are upregulated in POEMS syndrome." (PMID 27068711, 2016). "We hypothesize that the elevation of multiple inflammatory pathways in POEMS syndrome together with high IL-6 may influence VEGF levels though this requires further evaluation in larger datasets or prospective studies." (PMID 40646134, 2025). "The high titer of serum VEGF and IL-6 could explain common characteristic endovascular lesions of POEMS syndrome." (PMID 35133575, 2022). "Besides VEGF, other pro-angiogenic and pro-inflammatory factors, such as basic fibroblast growth factor, hepatocyte growth factor, tumor necrosis factor-α, IL-6, and IL-12, are elevated in POEMS syndrome." (PMID 34025681, 2021). "The pathogenesis of POEMS syndrome is not well understood, but overproduction of proinflammatory cytokines, such as interleukin (IL)-1β, IL-6, tumor necrosis factor (TNF)-α, and vascular endothelial growth factor (VEGF), has been reported and could play very important etiological roles." (PMID 23251183, 2012). "POEMS syndrome, on the other hand, is characterized by significantly elevated VEGF levels, along with increased inflammatory cytokines such as IL‐1β, IL‐6, and TNF-α." (PMID 41293360, 2025). "Second, in POEMS syndrome there is overproduction of proinflammatory cytokines, including TNFα, IL1β, IL10, IL6, VEGF, similarly to what is observed in MCD and KICS, suggesting that these three clinical entities partially overlap." (PMID 25607954, 2015). "The pathogenesis of POEMS syndrome remains largely unknown, though the overproduction of pro-inflammatory cytokines such as TGF-β1, IL-6, and VEGF play a key role in its development." (PMID 40589976, 2025). "The pathogenesis of POEMS syndrome is not well understood but it is thought to involve overproduction of proinflammatory cytokines, such as vascular endothelial growth factor (VEGF), interleukin-1 beta (IL-1B), interleukin-6 (IL-6), and tumor necrosis factor-alpha (TNF-alpha)." (PMID 34692278, 2021). "Finally, pro-inflammatory cytokines, such as tumor TNF-α, IL-6, and IL-12, which are upregulated in POEMS syndrome, were not evaluated, and this should be performed in future studies." (PMID 34167480, 2021).
primary effusion lymphoma (13 papers, 2017 to 2025). A large B-cell lymphoma located in the body cavities, characterized by pleural, peritoneal, and pericardial fluid lymphomatous effusions and that is always associated with human herpes virus-8 (HHV-8). "Moreover, quercetin inhibited IL-6 and IL-10 cytokine production, resulting in the cytotoxicity of primary effusion lymphoma (PEL)." (PMID 40427522, 2025). "Triptolide inhibited IL-6/STAT3 to reduce ascites formation and organ infiltration of primary effusion lymphoma." (PMID 36700235, 2022). "The dependency of PBL on IL-6 secretion and the PBL morphology suggests PBL are biologically related to primary effusion lymphoma." (PMID 28860565, 2017). "Capsaicin could induce apoptosis in KSHV-positive primary effusion lymphoma through the suppression of ERK and p38MAPK signaling and IL-6 expression." (PMID 31777601, 2019).
Sciatica (13 papers, 2011 to 2025). Pain in the lower back and hip radiating in the distribution of the sciatic nerve. "Seventeen key cytokines, chemokines and matrix metalloproteinases (MMPs) implicated in sciatica pathogenesis including TNFα and IL-6, were assayed in duplicate using commercial multiplex detection kits and measured using a Luminex suspension array system." (PMID 31077179, 2019). "The role of IL6 and in particular the effect of three common promoter polymorphisms (rs1800797, rs1800796, rs1800795) has been studied previously for the presence of sciatica, but also in relation to DD among 12- to 14-year-old children." (PMID 22107760, 2011). "Previous observational studies have reported associations between elevated levels of certain inflammatory markers like TNF-α, IL-6, and IL-8 in the serum or cerebrospinal fluid of sciatica patients compared to healthy controls." (PMID 39015317, 2024). "A study on adult patients suffering from sciatica demonstrated that the number of days with back and leg pain and days on sick leave were significantly higher among subjects with the IL6 rs1800797, rs1800796, rs1800795, and rs13306435 haplotypes." (PMID 35335997, 2022). "IL-6 and IL-8 are both higher in severe sciatica patients, and IL-6 is correlates to low back pain frequency." (PMID 34354983, 2021). "The results of this study are in contrast to those of Wang who found elevated levels of TNFα and IL-6 in patients with severe sciatica (defined as pain level of > 3 on VAS)." (PMID 31077179, 2019). "We speculate that in the early-stages of sciatica, the accumulation of neutrophils and other immune cells released inflammatory mediators like IL-6, TNF-α, and CCL-2 at the injury site." (PMID 41424922, 2025). "Differential protein levels of IL-6 in tissues from participants with DH or DDD have been observed in vitro, with higher levels in samples from subjects with confirmed discogenic pain caused by DDD than in those with DH or sciatica." (PMID 26743937, 2016). "The serum concentrations of IL-6 and TNF-α are closely related to the severity of pain and functional impairment in sciatica." (PMID 41424922, 2025). "The rates of production of IL-6 and IL-8 in the AI and EXT categories of discs in low back pain are much higher than those found in those with sciatica." (PMID 22235381, 2011). "Previous studies have reported serum inflammatory biomarkers of sciatica, and these include TNF-α, IL-4, IL-6, IL-8, IL-10, IL-17, IL-21, T helper lymphocytes 17, phospholipase A2, C-reactive protein, C-X3-C motif ligand 1, C-C motif ligand 2 and mast cell proteinase-1." (PMID 33535986, 2021).
Streptococcus pneumonia (13 papers, 2013 to 2025). "HMPV strongly suppresses IL-1β transcription in response to LPS or heat-killed Pseudomonas aeruginosa and Streptococcus pneumonia, while enhancing mRNA levels of IL-6, TNF-α and IFN-β." (PMID 37435074, 2023). "The RYNM exhibited its therapeutic effects on Streptococcus pneumonia mainly via the regulation of cell proliferation and survival through the IL-6/IL-10/IL-17, Bax/Bcl-2, COX-1/COX-2, NF-κB and TNF-α signalling pathways." (PMID 33678123, 2021). "IL-6 also plays a role in fighting infection, as IL-6 has been proven in mice to be required for resistance against the bacterium Streptococcus pneumonia." (PMID 32104715, 2020). "Xin-Yi-Qing-Fei-Tang can reduce the nasal colonization of Streptococcus pneumonia, which causes sinusitis and increases tumor necrosis factor-alpha (TNF-α), interleukin-1 beta (IL-1β), interleukin-6 (IL-6), and monocyte chemotactic protein-1 (MCP-1) levels and the migration of macrophages." (PMID 33204289, 2020). "IL-6 induces hepcidin transcription in response to multiple infections including streptococcus pneumonia and influenza A. IL-6-knockout mice demonstrated impaired or absent hepcidin induction in response to an inflammatory stimulus." (PMID 32481481, 2020). "The protective role of IL-6 has been demonstrated in IL6−/− mice which exhibit higher mortality when infected with various pathogens including E. coli, Klebsiella pneumonia, or Streptococcus pneumonia." (PMID 23637741, 2013).